ENSG00000281938 (novel transcript)
Gene: Protein-coding gene on chromosome 5 (131,807,143 to 132,011,637, reverse strand). Ensembl gene ENSG00000281938.
Genetic constraint (gnomAD): Missense variants: 720 observed, 906.28 expected, observed/expected ratio (o/e) 0.79, 90% interval 0.75 to 0.85. Synonymous variants: 347 observed, 335.42 expected, observed/expected ratio (o/e) 1.03, 90% interval 0.95 to 1.13.